HSF1 (heat shock transcription factor 1)
Diseases named in the same sentence as HSF1 in open-access papers (continued):
Sharing a sentence is not in itself a finding about the gene and the disease.
cancer (continued). "Due to its central role in the stabilization of tumorigenic pathways leading to an enhanced capability for cells to exhibit the many hallmarks of cancer, HSF1 presents a promising therapeutic target." (PMID 40287736, 2025). "HSF1 has been recently reported to be involved in the tumorigenesis and progression of various cancers such as ovarian, pancreatic, breast, and hepatic cancers." (PMID 40002205, 2025). "It is worth noting that the degradation of HSF1 is of particular clinical relevance, since dysregulation of this mechanism has profound consequences in diseases such as cancer and neurodegenerative disorders." (PMID 40457168, 2025). "ATF5 upregulates tumorigenic genes, promoting cancer cell proliferation and invasion, while HSF1 helps cancer cells evade immune surveillance." (PMID 40680837, 2025). "During cancer treatment, HSF1 can reprogram the proteome to protect cancer cells from stress, which can lead to multi-drug resistance." (PMID 40002205, 2025). "HSF1 is chronically activated in a wide range of cancers and hijacked by cancer cells to promote their survival and malignant properties in harsh TMEs47." (PMID 41028522, 2025). "By using techniques such as CRISPR, RNA sequencing and chromatin immunoprecipitation sequencing, they discovered that blocking HSF1 or DBC1 reduces cancer cell growth and spread." (PMID 41028522, 2025). "Despite accumulating evidence for the role of HSF1 in cancer progression, little is known about the coregulators and regulatory mechanisms of HSF1 in cancer cells." (PMID 41028522, 2025). "Since cancer cells are addicted to the HSF1-regulated chaperone system, it represents an attractive tumor-selective therapeutic target." (PMID 40204953, 2025). "This study sheds light on the intricate role of SUMOylation in regulating HSF1 activity during proteotoxic stress and its implications for cancer therapy." (PMID 40617887, 2025). "Cancer cells, however, appear to keep HSF1 constitutively activated, indicating a state of “HSF1 addiction” driven by continuous cellular stress." (PMID 40287736, 2025). "In contrast to HSF1, which promotes tumor progression, the effects of other HSFs on cancer are more diverse." (PMID 40457168, 2025). "IER5 is known to generate a hypo-phosphorylated active form of HSF1 in various cancer cells, distinct from the canonical hyper-phosphorylated active form." (PMID 40002205, 2025). "In fact, greater than 7% (730/9,950) of human cancers had co-amplification of both HSF1 and MYC genes, which was a statistically significant co-occurrence using a Fisher exact test (P < 0.0001)." (PMID 39831777, 2025). "DYRK2 phosphorylates, stabilizes and activates HSF1, thus promoting tumor growth by maintaining proteostasis in cancer cells." (PMID 41028522, 2025). "While HSF1 offers protective effects in neurodegenerative diseases, its overexpression in cancer promotes tumor growth, highlighting its paradoxical nature." (PMID 40287736, 2025). "Some of the genes upregulated by HSF1 in cancer cells protect the cancer cells against the toxic effects of the therapeutic drugs, which can lead to drug resistance." (PMID 40002205, 2025). "The levels of HSF1 and HSPs are frequently elevated across different cancer types, correlating with poor prognosis." (PMID 40457168, 2025). "HSF1 thus presents a promising therapeutic target for cancer treatment, potentially in combination with HSP inhibitors to alleviate typical initiation of HSR upon their use." (PMID 40287736, 2025). "The established links between HSF1 and cell cycle regulation strongly indicate its role in cancer progression." (PMID 40287736, 2025). "NXP800 is an investigational anticancer agent that exerts its effects by inhibiting the HSF1 signaling pathway, a crucial regulator of the cellular stress response in cancer cells." (PMID 41235005, 2025). "HSF1 is involved in various processes, such as migration, invasion and proliferation in many cancers." (PMID 40870378, 2025).
cancer (continued). "In highly malignant cancer cells, HSF1 has been shown to drive a transcriptional program distinct from heat shock, which includes cell‐substrate adhesion receptors called integrins and components of the ECM." (PMID 40457168, 2025). "Collectively, these observations clearly highlight the role of celastrol as a potential activator of HSF1, with significant implications for cancer therapy." (PMID 40520012, 2025). "Increasing evidence indicated that HSF1 is overexpressed in various types of human cancers, further enhancing cancer cell EMT, and is associated with cancer invasiveness." (PMID 40981348, 2025). "Overexpression of HSF1 has been associated with an increased proportion of cells in the G1 phase, which may lead us to a conclusion that HSF1 could potentially play a role in the suppression of cancer growth, however, more probably points to a more complicated role in cell cycle regulation." (PMID 40287736, 2025). "As HSF1 is a master transcription factor regulating genes involved in protecting cells against proteotoxic stress, it also controls various genes related to cancer cell survival." (PMID 40002205, 2025). "Cancer cells often endure genomic instability and fluctuating microenvironments, conditions where elevated HSF1 activity, based on its reparative functions, likely support survival." (PMID 40287736, 2025). "These insights reinforce the established connection between HSF1 and tumorigenesis, highlighting its potential as a significant factor in cancer development and progression." (PMID 40520012, 2025). "HSF1 overexpression in many types of cancer reportedly enhances cell growth enables survival, alters metabolism, weakens immune response and promotes angiogenesis or epithelial-mesenchymal transition (EMT) as these cells enter a form of “HSF1 addiction”." (PMID 40287736, 2025). "Support for the role of HSF1 in cancer has been further reinforced by various independent studies using xenograft models." (PMID 40287736, 2025). "ROS played a critical role in these effects, with modulation of HSPs and heat shock factor 1 (HSF1) further disrupting cancer cell survival mechanisms." (PMID 40051570, 2025). "HSF1 provides critical stress relief and confers metastatic and survival advantages to cancer cells exposed to myriad stresses, including genotoxic, proteotoxic, hypoxic and shear stresses, in TMEs and during metastasis." (PMID 41028522, 2025). "Bisamide 26 exhibits significant antitumor activity by suppressing cancer cell proliferation through the inhibition of the HSF1 pathway." (PMID 40520012, 2025). "In melanoma, FBXW7α is either mutated or downregulated, correlating with an increase in nuclear HSF1 and cancer progression." (PMID 40457168, 2025). "This therapeutic mechanism is particularly effective in cancers that heavily rely on HSF1 for protection against stress-induced damage, as it weakens the cells’ defenses against therapeutic intervention." (PMID 39850800, 2024). "Given that PERK promotes cancer development, growth, survival, and evasion from antitumor immunity, it is plausible that PERK-induced phosphorylation and activation of HSF1 are associated with chemoresistance." (PMID 38474017, 2024). "Heat Shock Factor 1 (HSF1) is a major transcriptional factor regulating the heat shock response and has become a potential target for overcoming cancer chemoresistance." (PMID 39850800, 2024). "HSF1 is likely the most significant member of the HSF family in cancer, exhibiting the most intricate biological functions." (PMID 39248163, 2024). "Of note, a few of specific HSF1 inhibitors have been launched within last few years and some of them show their efficacy in advanced in vivo models of cancer." (PMID 38280079, 2024). "HSF1 has since also been recognized for its pro-oncogenic properties, contributing to cancer initiation, progression, and chemoresistance." (PMID 39850800, 2024).
cancer (continued). "This study is the first to demonstrate that phosphorylation of HSF1 confers resistance to cancer cells against USP7i-based chemotherapy." (PMID 38474017, 2024). "Many of these interactors modulate HSF1’s activity and HSF1-dependent gene expression and are well-recognized targets for cancer therapy." (PMID 39682216, 2024). "HSF1 activation allows cancer cells to overcome cell cycle checkpoints and provides rapid proliferation by some mechanisms." (PMID 39682216, 2024). "It has been demonstrated in a wide range of cancer types that HSF1 has a cytoprotective activity and supports cancer cell proliferation, survival, invasion, and metastasis." (PMID 38589452, 2024). "On the one hand, HSF1 induces a transcriptional program in CAFs that differs from that of adjacent cancer cells." (PMID 39243039, 2024). "HSF1 promotes tumor progression and tumorigenesis in cancer cells by promoting their survival and escaping programmed cell death." (PMID 38748048, 2024). "Since cumulating evidence supports the oncogenic properties of the Heat Shock Factor 1 (HSF1) transcription factor in various cancer types, we investigated its pathogenetic and therapeutic relevance in iCCA." (PMID 39243039, 2024). "Multiple signaling pathways in cancer cells activate HSF1 to accommodate the rapidly changing tumor environment and stress of rapid cell proliferation." (PMID 39433125, 2024). "Under heat stress, BAG3 has been identified as a main regulator of nucleocytoplasmic shuttling of HSF1 in both cancer and normal cells." (PMID 39682216, 2024). "Consistent with its oncogenic role, HSF1 is overexpressed or overactivated in a broad spectrum of cancers and negatively correlated with the prognosis of cancer patients." (PMID 39261452, 2024). "HSF1 also has additional functions in cancer, including the development of dangerous signatures through the use of ERK, PKA and TOR56." (PMID 38956273, 2024). "HSF1 is increased in expression and facilitates cancer transformation by modulating signaling pathways related to growth and proliferation, apoptosis, metabolism, and motility." (PMID 39057095, 2024). "Overall, the study highlights aptamers’ potential for precise inhibition of HSF1 in cancer while minimizing off-target effects, providing a novel strategy to suppress cancer cell growth and survival by blocking HSF1’s DNA-binding activity." (PMID 39850800, 2024). "HSF1 is activated in cancer from reactive oxygen species, protein damage due to oxidative stress, mTOR hyper-activation, increased RAS/MAPK signaling, proteomic imbalance from aneuploidy, and destabilized protein folding from various genetic modifications." (PMID 38172561, 2024). "An increasing number of studies has summarized that HSF1 achieves its cancer-promoting effects by inhibiting cell apoptosis, accelerating cell proliferation and migration, reprogramming metabolic programs, and supporting the tumor microenvironment." (PMID 39261452, 2024). "HSF1 plays a multifaceted role in carcinogenesis, being vital for cancer adaptation and survival under challenging pathophysiological conditions like hypoxia, acidosis, ATP deprivation and nutritional changes 60-62." (PMID 38646654, 2024). "This article highlights the significance of HSF1 in cancer chemoresistance and its potential as a target for enhancing cancer treatment efficacy." (PMID 39850800, 2024). "Investigating the roles of PTMs on HSF1 in the cytosol would provide a better understanding of HSF1’s role in HSR and cancer progression and reveal if there are cytosolic ramifications of HSF1 PTMs." (PMID 39433125, 2024). "Conversely, HSF2 was recently reported to physically interact with HSF1 in several types of cancer, and this interaction promotes the expression of HSPs and non-HSP transcriptional targets to support tumor malignancy." (PMID 39682216, 2024).
cancer (continued). "In summary, these advancements are driving the development of more effective HSF1-targeted therapies to tackle the issue of chemoresistance in cancer treatment specifically." (PMID 39850800, 2024). "It is noteworthy that HSF1 has recently been discovered to play a significant regulatory role in tumor immunity, and is recognized as potential target in cancer immunotherapy." (PMID 39350280, 2024). "Concerning the regulatory mechanisms of Prom2 transcription, the activation of p38MAP kinase has been implicated in the phosphorylation and activation of the Heat Shock transcription factor HSF1 to drive Prom2 upregulation in cancer cells." (PMID 38757782, 2024). "Identifying the critical players responsible for the survival of cancer cells depleted of HSF1 will be highly helpful for innovative therapies combining HSF1 inhibitors with other drugs." (PMID 39243039, 2024). "This review comprehensively examines HSF1’s role in chemoresistance and its potential as a therapeutic target in cancer." (PMID 39850800, 2024). "We address this important issue by exploring the role of heat shock factor 1 (HSF1), a transcription factor that is highly expressed across several types of cancer and has a crucial role in tumor survival, in protecting against copper-mediated cytotoxicity." (PMID 39519208, 2024). "In aggressive cancers, Hsf1 is often hyperactivated or overexpressed due to Hsf1 locus amplification." (PMID 38260373, 2024). "In cancer cells, post-translational modifications are one of the major instruments to regulate HSF1 activity." (PMID 39682216, 2024). "This inhibition of NHEJ by HSF1 contributes to chemoresistance by promoting genomic instability, which can drive cancer progression and resistance to therapy." (PMID 39850800, 2024). "Overall, the present study provided a possible therapeutic strategy based on the combined treatment with USP7i and HSF1- or PERK-targeting drugs for effectively killing cancer cells." (PMID 38474017, 2024). "Our findings uncover how HSF1 protects against copper-induced damage in cancer cells and thus represents a novel therapeutic target for enhancing copper-mediated cancer cell death." (PMID 39519208, 2024). "Mechanistically, PERK activates and phosphorylates HSF1, thereby conferring resistance to USP7i-induced cancer cell death." (PMID 38474017, 2024). "Further studies are needed to elucidate the mechanism by which HSF1 regulates metal ion transporters and the Fe–S cluster protein expression in multiple cancer cell types, which is the project we are now working on." (PMID 39519208, 2024). "HSF1 is a downstream effector of the RAS-MEK pathway and KRAS-mutant cancers, due to their elevated levels of cellular stress resulting from rapid proliferation and metabolic demands, have a higher dependence on HSF1." (PMID 39850800, 2024). "Given this understanding, targeting HSF1 in various cancers appears to be a promising therapeutic strategy." (PMID 39850800, 2024). "Our unbiased transcriptome and biochemical analysis showed that HSF1 and its target genes associated with HSR and the unfolded protein response (UPR) were upregulated in USP7i-treated cancer cells." (PMID 38474017, 2024). "Previous studies have indicated that heat shock transcription factor 1 (HSF1) serves as a marker for a widespread metastatic program found in various cancers." (PMID 38804617, 2024). "Emerging evidence also highlights HSF1’s involvement in remodeling the tumor immune microenvironment as well as in the maintenance of cancer stem cells." (PMID 39682216, 2024). "In many types of cancer, heat shock factor 1 (HSF1) is a transcription factor activated under environmental stress, which leads to increased expression of HSP proteins." (PMID 39057095, 2024). "The primary goal of this review is to highlight the multiple interactions between HSF1 and its partners, with the hope that by modulating such interplays, HSF1 activity in cancer cells can be efficiently targeted." (PMID 39682216, 2024).
cancer (continued). "Earlier we reported another powerful inhibitor of HSF1, CL-43, which showed its anti-cancer activity being alone and in combination with clinically approved medicines." (PMID 38280079, 2024). "Apart from targeting HSF‐1, another promising avenue in cancer treatment is focusing on the dynamic chaperone cycle of HSP90." (PMID 38283176, 2024). "For example, the regulation of heat shock transcription factor 1 (HSF1) by TRPV1 has been explored as a mechanism to amplify cancer thermo-immunotherapy, providing a novel approach to cancer treatment." (PMID 39407657, 2024). "Heat shock factor protein 1 (HSF1), a central transcription factor in stress response pathways, exhibits markedly elevated activity in cancer." (PMID 39495731, 2024). "Firstly, while we have provided insights into HSF1 protein expression, enriching our dataset with more comprehensive profiling across diverse conditions and stages of cancer progression is necessary to enhance the depth of our findings." (PMID 39248163, 2024). "Our findings reveal that HSF1 protects cells from copper-reduced cell viability; thus, combining HSF1 inhibition with copper treatment represents a novel therapeutic strategy for cancer treatment." (PMID 39519208, 2024). "Cancer cells are stressed when subjected to chemotherapeutic drugs, which can activate HSF1 and the transcription of HSP70 and HSP90, further contributing to therapeutic resistance." (PMID 37958341, 2023). "On the contrary, in cancer cells, HSF1 is constitutively activated and its target genes are avidly expressed." (PMID 37153737, 2023). "Our laboratory, and others have shown that HSF1 can modulate glucose metabolism, and mediates tumorigenesis, cell proliferation and drug resistance in cancer cells 3, 7-10." (PMID 37153737, 2023). "Given the essential role of HSF1 in cancer, researchers are discovering the functions of HSF1 in tumorigenesis and developing HSF1 inhibitors as part of innovative targeted therapy." (PMID 37958341, 2023). "Later data demonstrated increased levels of HSF1 mRNA in many cancer types, suggesting regulation of HSF1 expression at the transcriptional level." (PMID 37894333, 2023). "It was found that HSF1 expression was significantly increased in HCC, compared to normal tissue; the increased expression of HSF1 was associated with cancer stages in HCC." (PMID 36482717, 2023). "To do so, we induced the Heat Shock Response pathway in two different cancer cell lines with two different stimuli and related the binding of its master regulator HSF1 to nascent RNA and chromatin accessibility." (PMID 37973875, 2023). "In this article, we examine the basic function of HSF1 and its regulatory mechanisms, focus on the mechanisms involved in HSF1′s roles in different cancer types, and examine current HSF1 inhibitors as novel therapeutics to treat cancers." (PMID 37958341, 2023). "HSF1 is overexpressed in multiple cancer types, and its activation supports malignancy and leads to poor prognosis." (PMID 37958341, 2023). "HSF1 is overexpressed in cancer cells and contributes to tumor cell migration, invasion, and proliferation." (PMID 37893084, 2023). "Once HSF1 is phosphorylated, the elevated levels of PD-L1 will then exacerbate immune escape, leading to cancer cell proliferation." (PMID 37153737, 2023). "The HSF1 pathway represents an attractive therapeutic target as it plays an important role in cancer initiation and in cancer progression and chemoresistance." (PMID 36622366, 2023). "As HSP expression is highly modulated by environmental aggressions, HSPs further accumulate in cancer cells after anti-cancer treatments through the induction/activation of the HSPs’ transcription factor HSF1." (PMID 36765939, 2023). "The mechanisms of HSF1-induced tumorigenesis are complex and involve diverse pathways, depending on the cancer type." (PMID 37958341, 2023).